ANKRD1 (ankyrin repeat domain 1)
Diseases named in the same sentence as ANKRD1 in open-access papers (continued):
Sharing a sentence is not in itself a finding about the gene and the disease.
hepatitis C virus infection (3 papers, 2016 to 2023). A viral infection caused by the hepatitis C virus. "We highlight the ANKRD1 gene, which was found to be induced in hepatitis C virus infection." (PMID 37233274, 2023). "It has been shown previously that ANKRD1 expression is increased in hepatic stellate cells during liver regeneration and upon Hepatitis C Virus infection, suggesting a role of ANKRD1 in liver function under stress, while it is unclear how this muscle specific gene is turned on in liver diseases." (PMID 33553074, 2020).
hepatoma (3 papers, 2016 to 2020). "It has been reported previously that ectopic expression of ANKRD1 led to enhanced apoptotic cell death in hepatoma cells." (PMID 26860204, 2016). "Previous study shows that ANKRD1 expression in hepatoma cells is increased by exposing cells to the apoptogenetic drug Fenretinide16." (PMID 26860204, 2016).
lung adenocarcinoma (3 papers, 2018 to 2024). A carcinoma that arises from the lung and is characterized by the presence of malignant glandular epithelial cells. "In the present study, we first demonstrated that ANKRD1 was commonly involved in anti-apoptosis and resistance to EGFR-TKIs in lung adenocarcinoma." (PMID 30291293, 2018). "Inhibition of ANKRD1 led to induction of apoptosis by afatinib or osimertinib in adenocarcinoma cells, providing a critical therapeutic target for resistance to EGFR-TKIs in lung adenocarcinoma." (PMID 30291293, 2018). "In accordance, both in lung adenocarcinoma (LUAD) and in lung squamous cell carcinoma (LUSC) patients, the EZH2 mRNA has a negative correlation with CTGF, ANKRD1 and CYR61 transcripts." (PMID 39455556, 2024).
mesothelioma (3 papers, 2017 to 2024). A usually malignant and aggressive neoplasm of the mesothelium which is often associated with exposure to asbestos. "Cox regression analysis found that ANKRD1 expression was related to overall survival (OS) in 14 types of cancer, including bladder urothelial carcinoma (BLCA), CESC, COAD, diffuse large B-cell lymphoma (DLBC), GBM, HNSC, KIRC, KIRP, LGG, LIHC, LUSC, mesothelioma (MESO), PAAD, and STAD (P < 0.05)." (PMID 38438492, 2024).
prostate carcinoma (3 papers, 2017 to 2024). A carcinoma that arises from epithelial cells of the prostate gland. "Interestingly, we found that ANKRD1 is epigenetically inactivated in several cancer cells including lung and prostate cancer." (PMID 29179447, 2017). "We observed prominent induction of several classic YAP/TAZ target genes in prostate cancer, including CTGF, CYR61, and ANKRD1, yet this enrichment of YAP/TAZ downstream targets was less striking in the comparisons of breast subsets." (PMID 35520391, 2022).
skin cancer (3 papers, 2017 to 2024). "Targeting ANKRD1 disrupts AP-1 complex formation, reverses CAF activation, and blocks the pro-tumorigenic properties of CAFs in an orthotopic skin cancer model." (PMID 38310103, 2024).
atherosclerosis (2 papers, 2022 to 2024). A disease characterized by the build-up of fatty material and calcium deposition in the arterial wall resulting in partial or complete occlusion of the arterial lumen. "The expression of Ankrd1 is modulated by several cytokines and growth factors implicated in atherosclerosis." (PMID 39420247, 2024). "Activin A, known as an inhibitor of atherogenic processes, was found to enhance Ankrd1 expression in SMCs, suggesting a protective role of Ankrd1 in atherosclerosis." (PMID 39420247, 2024). "Ankrd1 plays a multifaceted role in atherosclerosis, acting both as a modulator of inflammatory responses and as a regulator of cell proliferation within the vascular wall." (PMID 39420247, 2024). "Inflammatory cytokines such as IL-1 and TNF-α, along with TGF-β—a critical mediator of vascular remodeling and atherosclerosis—have been identified as potent inducers of Ankrd1 expression." (PMID 39420247, 2024).
colorectal cancer (2 papers, 2024). A primary or metastatic malignant neoplasm that affects the colon or rectum. "Increased expression of Ankrd1 has been linked to poor prognosis of colorectal cancer." (PMID 39420247, 2024). "By inhibiting apoptosis, Ankrd1 contributes directly to the tumorigenic process, promoting the metastasis and invasion of colorectal cancer cells." (PMID 39420247, 2024). "Colorectal cancer: Ankrd1 displayed increased expression in intestinal adenomas and was induced in mouse models of Wnt/β-catenin-induced tumors." (PMID 39420247, 2024). "In vitro experiments demonstrated that ANKRD1 promotes migration, and invasion activity, while inhibiting apoptosis in colorectal cancer cell lines (Caco2, SW480)." (PMID 38438492, 2024). "Therefore, we utilized lentivirus to mediate ANKRD1 expression in Caco2 and SW480 cell lines to observe any changes in the biological functions of colorectal cancer cells." (PMID 38438492, 2024). "Similarly, the ANKRD1 OE group in SW480 cells exhibited consistent results, suggesting that ANKRD1 does not significantly influence the proliferation of colorectal cancer cells." (PMID 38438492, 2024).
Duchenne muscular dystrophy (2 papers, 2020 to 2023). Duchenne muscular dystrophy (DMD) is a neuromuscular disease characterized by rapidly progressive muscle weakness and wasting due to degeneration of skeletal, smooth and cardiac muscle. "Finally, Chadwick and colleagues demonstrated that MR antagonism by spironolactone was able to downregulate the Ankrd1 transcript in a Duchenne muscular dystrophy (DMD) mouse model, thus identifying Ankrd1 as a novel MR gene target." (PMID 37108574, 2023).
idiopathic pulmonary fibrosis (2 papers, 2024 to 2025). Idiopathic pulmonary fibrosis (IPF) is a nonneoplastic pulmonary disease that is characterized by the formation of scar tissue within the lungs in the absence of any known cause. "More recently ANKRD1 was identified as a mesenchymal-specific transcriptional coactivator driving fibroblast activation in cancer but also in other conditions such as hypertrophic scarring and idiopathic pulmonary fibrosis." (PMID 40558566, 2025). "Moreover, ANKRD1 expression was considerably elevated in fibroblast-related pathologies such as hypertrophic scarring, keloids, and idiopathic pulmonary fibrosis, pointing to a likely common link with CAF activation." (PMID 38310103, 2024). "Importantly, we showed that ANKRD1 is also significantly elevated in fibroblasts from a variety of fibrotic diseases ranging from hypertrophic scarring, keloids, and idiopathic pulmonary fibrosis." (PMID 38310103, 2024).
kidney stone (2 papers, 2024). "Additionally, in renal epithelial HK-2 cells, Ankrd1 is markedly upregulated in response to calcium oxalate exposure, which mimics the conditions of kidney stone formation." (PMID 39420247, 2024).
melanoma (2 papers, 2024). A malignant, usually aggressive tumor composed of atypical, neoplastic melanocytes. "Elevated ANKRD1 expression was also found in melanoma-derived CAFs versus a reference panel of HDFs." (PMID 38310103, 2024). "We also found that although some established YAP/TAZ target genes (CRIM1, F3, ANKRD1) correlated strongly with CTGF and CYR61 expression in human melanoma, others did not (WWC1, FOSL1, FSTL3)." (PMID 38473214, 2024).
metastatic cancer (2 papers, 2017 to 2020). A carcinoma which has spread from the original site of growth to another anatomic site. "These included genes which are implicated in inflammation and inflammatory responses to cancer (PTX3, IL8, TNFSF10, SERPINB13 and ANKRD1) and those involved in cell adhesion, cell migration and ECM degradation of importance in metastatic cancer (MMP12, MMP1 and ADAM19)." (PMID 28555042, 2017). "Interestingly, we also found a lack of ANKRD1 expression induction in MeWo TPC2-silenced cells, maybe indicating a differential effect of reduced TPC2 expression on this gene in distinct types of metastatic cancer cells." (PMID 32846966, 2020).
Myocardial fibrosis (2 papers, 2022 to 2024).
osteosarcoma (2 papers, 2024). A usually aggressive malignant bone-forming mesenchymal neoplasm, predominantly affecting adolescents and young adults. "For instance, miR-3614-5p notably suppresses Ankrd1 expression in osteosarcoma cells by directly targeting the 3′ untranslated region (3′-UTR) of its mRNA, illustrating the specific post-transcriptional silencing mechanisms employed by cells." (PMID 39420247, 2024). "Osteosarcoma: in osteosarcoma (OSA), Ankrd1 is targeted by the tumor-suppressing miR-3614-5p, and its expression is regulated by the interaction with RGMB-AS1, a long non-coding RNA." (PMID 39420247, 2024).
pheochromocytoma (2 papers, 2024 to 2025). "We previously reported that Ankrd1 is induced by ERK5 in rat pheochromocytoma (PC12) cells and could detect Ankrd1 expression in surgical specimens of composite pheochromocytoma and ganglioneuroblastoma." (PMID 40362467, 2025).
renal fibrosis (2 papers, 2013 to 2024). A final common manifestation of a wide variety of chronic kidney diseases characterized by glomerulosclerosis and tubulointerstitial fibrosis. "Another study reported that TGF-β1-induced and unilateral ureter obstructive (UUO)-induced renal fibrosis also upregulated Ankrd1 expression." (PMID 39420247, 2024).
viral infections (2 papers, 2024 to 2025). "It is worth noting that ANKRD1 expression is also increased by stress, which is conducive to viral infections of the liver." (PMID 40415790, 2025). "The role of Ankrd1 extends beyond simple inflammatory responses to being a critical player in the host–pathogen interaction during various viral infections." (PMID 39420247, 2024). "Moreover, Ankrd1 has been implicated in human immunodeficiency virus (HIV) infection through its mediation of interactions between the HIV-1 envelope protein gp120 and the integrin receptor α4β7 on B cells, further emphasizing its role in the pathogenesis and immune response during viral infections." (PMID 39420247, 2024).
acute lymphoblastic leukemia (1 paper, 2024). Leukemia with an acute onset, characterized by the presence of lymphoblasts in the bone marrow and the peripheral blood. "In this context, Ankrd1 has emerged as a potential biomarker, particularly in pediatric acute lymphoblastic leukemia (ALL)." (PMID 39420247, 2024).
autoimmune myocarditis (1 paper, 2022). Autoimmune myocarditis is an autoimmune disease that affects the heart. "To address this, we induced experimental autoimmune myocarditis (EAM) in ANKRD1-deficient mice, and evaluated post-MC consequences at the DCM stage mice hearts." (PMID 36551326, 2022).
bladder cancer (1 paper, 2021). "Depletion of MINDY1 decreased the YAP protein level and the expression of YAP/TEAD target genes in bladder cancer, including CTGF, ANKRD1 and CYR61." (PMID 34315490, 2021).
breast tumor (1 paper, 2024). "Knockdown of ANKRD1 in highly metastatic breast tumor cells reduced the phosphorylation of IκKα and NF-κB." (PMID 39409926, 2024). "We confirmed that ANKRD1 promotes breast tumor metastasis, as the LM-2-ANKRD1 knockdown group showed lower signals in metastatic organs such as the lung and liver than the control vector group." (PMID 39409926, 2024). "In addition, we also observed strong ANKRD1 signals in high-grade human breast tumor tissues." (PMID 39409926, 2024).
cervical squamous cell carcinoma (1 paper, 2024). A squamous cell carcinoma arising from the cervical epithelium. "While ANKRD1 exhibited distinct expression levels between carcinoma and normal tissues, its expression remained stable across different clinical stages of pan-cancer, except for breast invasive carcinoma (BRCA), cervical squamous cell carcinoma (CESC), and KIRP (P < 0.05)." (PMID 38438492, 2024).
cholestasis (1 paper, 2018). Impairment of the bile flow caused by obstruction within the liver, or outside the liver in the bile duct system. "The co-treatment of GCA and VP gradually reduced expression levels of Sox9 and the YAP target genes Cyr61, Ctgf, Afp and Ankrd1 indicating a direct link between cholestasis mediated expression of Sox9 through activation of YAP, which is independent of RBPJ." (PMID 30501048, 2018).
colon adenocarcinoma (1 paper, 2024). "In addition, we utilized in vitro models to evaluate the impact of ANKRD1 on the proliferation, migration, and invasion of colon adenocarcinoma (COAD)." (PMID 38438492, 2024).
colon cancer (1 paper, 2017). "Here we show that ectopic expression of ANKRD1 reduces colony formation in prostate, lung and HCT116 colon cancer cells." (PMID 29179447, 2017).
diastolic heart failure (1 paper, 2013). Heart failure caused by abnormal myocardial relaxation during diastole leading to defective cardiac filling. "It has been reported that there is a left-right asymmetric distribution of Ankrd1, with increased level of expression in the left ventricle compared to right ventricle in a diastolic heart failure model." (PMID 23724005, 2013).
hepatopathy (1 paper, 2020). "Therefore, the ectopic expression of ANKRD1 in liver may imply its pathogenetic role in hepatopathy." (PMID 33553074, 2020).
Insulin resistance (1 paper, 2025). Increased resistance towards insulin, that is, diminished effectiveness of insulin in reducing blood glucose levels. "Interestingly, KEGG enrichment analysis demonstrated that the FoxO signalling pathway and insulin resistance were enriched in ANKRD1+ myonuclei, which have been shown to be related to muscle atrophy and adipocyte differentiation." (PMID 39435630, 2025).
juvenile dermatomyositis (1 paper, 2025). Juvenile dermatomyositis (JDM) is the early-onset form of dermatomyositis (DM), a systemic, autoimmune inflammatory muscle disorder, characterized by proximal muscle weakness, evocative skin lesion, and systemic manifestations. "As vasculopathy is central to the pathogenesis of juvenile dermatomyositis, the role of ANKRD1 as a mediator of myofibre response to abnormal blood flow may be further investigated to gain insight into the pathophysiology of myofibre ischaemic changes that occur in severe JDM." (PMID 40558566, 2025).
medulloblastoma (1 paper, 2020). A malignant, invasive embryonal neoplasm arising from the cerebellum. "Moreover, when analyzing all medulloblastoma subgroups, elevated ANKRD1 and NRG1 expression correlated with lower patient survival." (PMID 32316671, 2020). "Next, we moved our attention to genes already related to medulloblastoma based on the literature and validated some of them, such as POSTN, BOC, VCAM1, and TP63 among the downregulated genes and ANKRD1, THBS1, NRG1, PTHLH, and HBEGF among the upregulated ones in DAOY and D283Med cells." (PMID 32316671, 2020). "Finally, we correlated their expression with patient outcome finding that altered VCAM1, TP63, ANKRD1, THBS1, and PTHLH levels correlated with lower patient survival in Group 4 medulloblastoma samples." (PMID 32316671, 2020).
motor neuron disease (1 paper, 2016). "Ankrd1 has been found to be increased in response in several forms of muscle injury, including denervation, motor neuron disease, stretch, and starvation." (PMID 27891095, 2016).
muscle atrophy (1 paper, 2014). The loss of muscle tissue due to inactivity or disease. "We focused this analysis on four genes that are closely linked to muscle atrophy (MSTN) and fast‐twitch, glycolytic muscle properties (ANKRD1, MYH8 and MYCBP2)." (PMID 24744911, 2014).
muscular atrophy (1 paper, 2019). "The large, easily detected increase in Ankrd1 makes it an attractive target for evaluating muscular atrophy models." (PMID 30906768, 2019). "The increase in Ankrd1 expression during muscular atrophy has been reported as up to an order of magnitude higher than that of other markers such as MAFbx and MuRF1." (PMID 30906768, 2019).
myocarditis (1 paper, 2024). Myocarditis is a condition that is characterized by inflammation of the heart muscle (myocardium). "Mice models deficient in Ankrd1 expression showed reduced cardiac remodeling and preserved contractility when challenged with myocarditis-induced DCM." (PMID 39420247, 2024). "Additionally, myocarditis, a common precursor to DCM, has been linked to changes in Ankrd1 expression." (PMID 39420247, 2024).
Nephropathy (1 paper, 2022). A nonspecific term referring to disease or damage of the kidneys. "Interestingly, blocking of mTORC2 with PP242, an mTOR kinase inhibitor, halted the expression of YAP/TAZ and their target genes CTGF and ankyrin repeat domain 1 (ANKRD1) in cultured fibroblasts and UUO-induced nephropathy." (PMID 35805148, 2022).
non-small cell lung carcinoma (1 paper, 2025). A group of at least three distinct histological types of lung cancer, including non-small cell squamous cell carcinoma, adenocarcinoma, and large cell carcinoma. "Ankrd1 induces apoptosis in ovarian and non-small cell lung cancer." (PMID 40362467, 2025).
Obesity (1 paper, 2018). Accumulation of substantial excess body fat. "We were able to further confirm the notion, that obesity alters satellite cell numbers and negatively affects the expression levels of Ankrd1, C3ar1, Ccl8, Mpeg1, and Myog, as seen in our qPCR results." (PMID 29922174, 2018).
osteoporosis (1 paper, 2024). A condition of reduced bone mass, with decreased cortical thickness and a decrease in the number and size of the trabeculae of cancellous bone (but normal chemical composition), resulting in increased fracture incidence. "Interestingly, the ectopic expression of Ankrd1 in this model can alleviate some effects of osteoporosis induced by ovariectomy, which is linked to the regulatory effects of estrogen on osteoclast formation and bone resorptive activity." (PMID 39420247, 2024). "Bilateral ovariectomy, a model for osteoporosis, leads to decreased expression of Ankrd1 in BMSCs." (PMID 39420247, 2024). "Additionally, the impact of Ankrd1 extends to pathological conditions such as osteoporosis." (PMID 39420247, 2024).
ovarian adenocarcinoma (1 paper, 2012). An adenocarcinoma that arises from the ovary. "Furthermore, up-regulation of ANKRD1 was associated with decreased sensitivity for cisplatin in ovarian adenocarcinoma." (PMID 22095227, 2012).
prostate adenocarcinoma (1 paper, 2024). "Furthermore, we found that the DNA methylation level of ANKRD1 was positively related to ANKRD1 expression in BLCA, COAD, KIRC, LIHC, and TGCT, but negatively associated with ANKRD1 expression in BRCA, HNSC, MESO, prostate adenocarcinoma (PRAD), and sarcoma (SARC)." (PMID 38438492, 2024).
renal failure (1 paper, 2024). "ANKRD1 was found to be upregulated in both IRI‐AKI mouse models and in vitro models, and inhibiting ANKRD1‐mitigated renal failure in mice and damage of HK‐2 cells." (PMID 39285846, 2024).